LEP (leptin)
Diseases named in the same sentence as LEP in open-access papers (continued):
Sharing a sentence is not in itself a finding about the gene and the disease.
cardiovascular disease (continued). "Due to its trafficking function, the GOSR2 gene could be associated with the cardiovascular diseases which are highly associated with macromolecules such as insulin, leptin, and angiotensinogen." (PMID 29137253, 2017). "The higher leptin levels observed among participants born with a low weight might partly contribute to this observation, as higher leptin levels have been shown to be an independent risk factor for cardiovascular disease among diabetic patients." (PMID 27141948, 2016). "The MESA cohort includes individuals free of clinical cardiovascular disease, which might explain the inverse associations with RV mass, whereas studies showing adverse effects of leptin are from patients with clinical cardiovascular disease." (PMID 26348768, 2015). "Given the current state of knowledge, the potential significance of the studied adipokines, especially ADPN and the ADPN/LEP ratio, as a valuable complementary diagnostic element in the prediction and prevention of cardiovascular diseases needs further research." (PMID 26389928, 2015). "Furthermore, L. plantarum administration leads to a reduction in cardiovascular disease risk factors such as systolic blood pressure, leptin, and fibrinogen in smokers consuming 400 mL/d of a rose-hip drink containing L. plantarum 299v (5 × 107 CFU/mL) for 6 weeks." (PMID 32509880, 2020). "Considering the roles of leptin in physiological processes associated with cardiovascular disease, such as blood pressure, platelet aggregation, arterial thrombosis, angiogenesis, and inflammatory vascular responses, it, logically, may have a close relationship with the development of CVD." (PMID 27663646, 2016). "Leptin levels are associated with favorable RV morphology in a multi-ethnic population free of cardiovascular disease, however these associations may be explained by a yet to be understood bi-ventricular process as this association was no longer present after adjustment for LV values." (PMID 26348768, 2015). "While adipokines like adiponectin, apelin, and omentin have anti-inflammatory and cardioprotective properties, others like leptin, resistin, and visfatin exert pro-inflammatory effects, contributing to cardiovascular disease." (PMID 40362168, 2025). "T2DM is a major risk factor for cardiovascular diseases, including ACS, and leptin is known to influence insulin sensitivity and glucose metabolism." (PMID 40362168, 2025). "Leptin likely participates in the development of cardiovascular diseases through both indirect and direct processes." (PMID 38256208, 2024). "To contribute to this knowledge, we have reviewed the literature to underscore the potential role of leptin in cardiovascular disease among obese patients with T2DM." (PMID 38397015, 2024). "And future studies are needed to elucidate and comprehensively understand the interaction of leptin with circadian rhythm genes and sodium/potassium ion transport channels under hypoxia-induce cardiovascular diseases." (PMID 38702334, 2024). "Next to inflammatory markers and endothelial cell activation markers also adipokines, such as leptin, appear to play a role in cardiovascular disease." (PMID 39012360, 2024). "Based on these effects, leptin is attributed to a significant role in the development of cardiovascular diseases." (PMID 36901837, 2023). "Leptin, a neuroendocrine hormone released by adipose tissue, has a complex relationship with cardiovascular diseases, including PAH." (PMID 37869164, 2023). "In studies based on clinical data, there have been controversial reports about the role of leptin in cardiovascular disease." (PMID 35056647, 2022). "Cardiovascular disorders occur with insufficient adiponectin and leptin signaling, yet, in pathogenesis of cardiovascular disorders, elevated levels of both leptin and adiponectin are found." (PMID 35890325, 2022).
cardiovascular disease (continued). "Since its discovery, leptin has become known as a pectoral muscle hormone that is widely studied in the context of cardiovascular disease and is important in the supervision of ventilation control." (PMID 35162313, 2022). "Like leptin, adiponectin was also the most frequently examined adipokines relevant to cardiovascular disorders." (PMID 35145478, 2021). "The relationship between leptin and mTOR signaling, and its implication in pathophysiological conditions such as cardiovascular diseases, has been previously discussed and reviewed in the literature." (PMID 33316969, 2020). "Leptin high concentration improves oxidative stress and inflammation and above all cardiovascular diseases." (PMID 33171610, 2020). "The aim of the present study was to clarify the pathophysiological roles of circulating serum leptin and adiponectin in patients with cardiovascular disease (CVD) receiving cardiovascular surgery." (PMID 31703113, 2019). "The aim of the present study was to assess the relationship between serum leptin and adiponectin levels and echocardiographic parameters and pathophysiological states in patients with cardiovascular disease (CVD) receiving cardiovascular surgery." (PMID 31703113, 2019). "The role of leptin as a pathophysiological modulator has been described in other canine pathological conditions, besides cardiovascular diseases." (PMID 31091785, 2019). "We recently determined the levels of fatty acid-binding protein 4 (FABP4), leptin, and adiponectin in not only the circulation but also the pericardial fluid from a small number of cardiovascular disease patients." (PMID 30395653, 2018). "In terms of surrogate markers of cardiovascular disease, authors recorded significantly decreased circulating leptin concentrations in mice fed with HT as compared with controls." (PMID 28335517, 2017). "In this regard, various studies have shown that plasma leptin levels are elevated whereas adiponectin levels are decreased in patients with cardiovascular disease." (PMID 26731409, 2016). "Beside, the positive correlation between leptin and DBP in this study is in accordance with observational data associating leptin with cardiovascular disease, as well as the positive association found with plasma total cholesterol." (PMID 27189377, 2016). "Due to the presence of LEP receptors in many tissues, e.g., in cardiomyocytes (LEPRa, -b and -c isoforms), it seems possible that LEP plays a certain role in the pathogenesis of cardiovascular diseases." (PMID 26389928, 2015). "While further information is required, these findings imply that targeting at leptin would be a potential strategy to combat cardiovascular disease in patients with SLE." (PMID 24790989, 2014). "Leptin has peripheral actions to stimulate vascular inflammation, oxidative stress and cardiovascular disease." (PMID 25083175, 2014). "The probiotic bacterium Lactobacillus plantarum 299 v was able to affect hallmarks of cardiovascular disease in smokers, i.e. reduce systolic blood pressure, leptin and fibrinogen levels." (PMID 23056479, 2012). "When L. plantarum 299v was supplemented to the diet of smokers, the serum levels of leptin and fibrinogen and LDL-cholesterol, the risk factors for cardiovascular disease, were also reduced." (PMID 23049548, 2012). "In terms of cardiovascular disease, plasma leptin levels are reported to be an independent predictor of early atherosclerotic events such as intima-media thickness." (PMID 20150963, 2009). "Serum concentrations of proteins associated with risk for cardiovascular disease, including C-reactive protein (CRP), soluble intercellular adhesion molecule-1 (sICAM-1), and leptin, were also measured." (PMID 18775082, 2008). "Among those reported to be independent predictors of cardiovascular disease risk are C-reactive protein (CRP), soluble intercellular adhesion molecule-1 (sICAM-1), and leptin." (PMID 18775082, 2008).
cardiovascular disease (continued). "In addition to its metabolic functions, leptin exhibits potent pro-inflammatory effects that play a significant part in cardiovascular disease development." (PMID 40421192, 2025). "Moreover, leptin and adiponectin are involved in inflammation, as well as metabolic functions and cardiovascular diseases." (PMID 38737668, 2024). "However, the interplay between leptin and adiponectin, another adipokine, is crucial in influencing the progression of cardiovascular disease." (PMID 38397015, 2024). "Twenty-four-hour ambulatory, but not clinic BP, already associates with leptin in young adults with OW/OB, but without overt cardiovascular disease." (PMID 37872379, 2024). "Recent insights concerning chronic joint inflammation and its role in cardiovascular disease are relevant, and met-inflammation, adipokines and leptin might play a crucial role in explaining the linkage." (PMID 35784017, 2022). "In addition, leptin can serve as the regulator of cardiovascular function in the physiological range, and plasma leptin levels can be used as a biomarker for cardiovascular diseases." (PMID 34557167, 2021). "Elevated plasma leptin positively correlates with cardiovascular disease." (PMID 32752134, 2020). "Animal studies using leptin- and leptin receptor- (Lepr) deficient rodents have provided many useful insights into the underlying molecular and pathophysiological mechanisms of obese- and T2DM-associated metabolic and cardiovascular diseases." (PMID 32655492, 2020). "In the present study, we hypothesized that circulating proteins could be mediators that link leptin with the development of cardiovascular disease." (PMID 32753620, 2020). "Moreover, an increasing number of studies have analyzed or polyphenolic compounds potential benefits in impaired leptin signaling and cardiovascular diseases." (PMID 33171610, 2020). "Furthermore, high circulating levels of leptin appeared to induce significant impairment of the haemostatic balance in cardiovascular diseases." (PMID 31091785, 2019). "The actions of leptin in the cardiovascular system may help explain the link between excess body fat mass and cardiovascular diseases." (PMID 31500090, 2019). "Leptin also increases ROS production and oxidative stress, which might explain the recently reported increases in cardiovascular disease among diabetic patients." (PMID 30774721, 2019). "Thus, leptin targeting the GSK3/OMA1/OPA1 signaling pathway can optimize hMSCs therapy for cardiovascular diseases such as MI." (PMID 29748581, 2018). "Of note, the L/A ratio may represent a preferential marker compared to leptin and adiponectin alone in predicting incident cardiovascular disease." (PMID 28077136, 2017). "Furthermore, positive associations between leptin, PAI-1 and cardiovascular disease have been documented." (PMID 28552966, 2017). "Two adipokines which are likely of particular importance to cardiovascular function, leptin and adiponectin, exert opposite effects on the heart and their plasma concentrations are changed in diametrically different directions under cardiovascular disease states." (PMID 26731409, 2016). "In the men serum leptin also provided information about risk that was independent of two strong non-invasive markers of cardiovascular disease, carotid IMT and carotid-femoral PWV." (PMID 25994184, 2015). "Factors such as angiotensinogen, adiponectin, leptin, angiotensin-converting enzyme and plasminogen activator inhibitor-1 (PAI-1) are all secreted from adipose tissue and have been implicated in the development of cardiovascular disease in the offspring." (PMID 22194901, 2011). "The present study explores whether the widely found cardiovascular diseases (CVD) risk effects of ACE I/D, APOE (ε2, ε3, ε4), eNOS-VNTR and LEP G2548A polymorphisms can be replicated in this specific population." (PMID 21244662, 2011).
cardiovascular disease (continued). "We found that leptin concentrations were increased in the SCI-IA group compared to the SCI-PA and control cohorts, suggesting that lower levels of physical activity may indicate a greater risk of cardiovascular disease in people with SCI." (PMID 34621899, 2021). "The controversy about the involvement of leptin in cardiovascular diseases may be explained by the disparity between its beneficial and detrimental effects including the widespread cardiovascular and dose-dependent effects of leptin as well as the concept of selective leptin resistance." (PMID 31500090, 2019). "Notably, emerging data suggest that the ratio of leptin-to-adiponectin (L/A) levels may be a better indicator of the risk of cardiovascular disease and mortality in CKD, as it holistically accounts for both pro-atherogenic leptin and anti-atherogenic adiponectin concentrations." (PMID 41295840, 2025). "GrimAge is based on seven plasma protein levels related to various diseases and conditions, including cardiovascular disease (Plasma B2M) and cognitive functions (Plasma B2M, ADM, Cystatin C, and leptin)." (PMID 40699219, 2025). "Apart from the effect of LEPR on the JAK/STAT pathway, Hou and Luo have suggested a relationship between the leptin, JAK/STAT and mitogen-activated protein kinases (MAPK) signal pathways with an effect on cardiovascular diseases." (PMID 34496773, 2021). "We examined relationships of leptin, resistin, TNF-α, and adiponectin with RV morphology and function (from cardiac MRI) in participants (n = 1,267) free of clinical cardiovascular disease from the Multi-Ethnic Study of Atherosclerosis (MESA)-RV study." (PMID 26348768, 2015). "Amongst various atherogenic adipokines, leptin has been most extensively and systematically studied in patient with SLE, in relation to premature atherosclerosis and cardiovascular disease." (PMID 24790989, 2014). "However, some authors introduced the concept of ‘selective leptin resistance’ in 2002 to explain how leptin might increase the blood pressure in obese individuals, although the net effects of hyperleptinaemia on cardiovascular diseases are still not clearly understood." (PMID 34208585, 2021). "It has been suggested that the vascular effects of leptin may begin early in life, even in non-obese but slightly overweight young subjects, and subsequently, the prolonged action of leptin on the vasculature may increase the risk of adult cardiovascular disease onset." (PMID 34202323, 2021). "They saw increased CRP concentrations at very high serum leptin levels and concluded; CRP did not predict cardiovascular disease independently, unlike leptin, which maintained a statistically significant predictive power." (PMID 34178553, 2021). "The role of hyperleptinemia in cardiovascular diseases is well known; however, in the renal tissue, the exact site of leptin’s action has not been established." (PMID 25793389, 2015). "Present analysis showed that the Bayash Roma of Croatia, in comparison with other European populations, do not carry an increased genetic risk for cardiovascular diseases related to the most common polymorphisms of the ACE, eNOS and LEP genes." (PMID 23390466, 2012). "In metabolic and cardiovascular disease states, EAT reduces the production of cardioprotective adipocytokines, such as adiponectin, and induces the production of detrimental pro-inflammatory adipocytokines such as leptin, resistin, IL-6, tumor necrosis factor-α, and IL-17." (PMID 23409197, 2013). "The potential role of LEP and ADPN in the pathology of cardiovascular diseases is not limited to the impact on blood pressure." (PMID 26389928, 2015).
infection (180 papers, 2007 to 2026). The state of being infected such as from the introduction of a foreign agent such as serum, vaccine, antigenic substance or organism. "Monocytes regulated hypodermal adipocytes and associated leptin-mediated revascularization of wounds post-infection." (PMID 40667795, 2025). "Collectively, leptin replacement in deficiency states can restore T cell survival, metabolism, and memory, thereby enhancing vaccine responses and resistance to infection." (PMID 41516046, 2025). "A study in Brazil found that infection with P. vivax was associated with placental lesions and an imbalance in homeostasis, as well as altered angiogenic factors, leptin, and cytokines." (PMID 41310743, 2025). "The disruption of lymphoid tissue integrity by fat accumulation and altered secretion of adipocytokines, such as leptin or adiponectin, has been suggested to explain immune dysfunction and infection susceptibility in obese patients." (PMID 39858361, 2025). "infection before 24 weeks of gestation were associated with alterations of some proteins such as leptin and sENG." (PMID 41335627, 2025). "Numerous studies support the idea that leptin supplementation can reduce infections caused by pathogens such as Listeria monocytogenes, Klebsiella pneumoniae, Escherichia coli, and Mycobacterium tuberculosis by boosting macrophage phagocytosis." (PMID 40095902, 2025). "Leptin plays a crucial role in immunity, with leptin’s deficiency can increase susceptibility to infections." (PMID 39492784, 2024). "In vivo evidence in rodent models indicate that leptin-deficient ob/ob mice have impaired host defense against various infections, including Klebsiella pneumonia, influenza A, Listeria, among many others." (PMID 38031726, 2023). "In this fat pad, infection was associated with moderate decreased adipocyte number, increased release of leptin, visfatin and chemerin, and decreased release of adiponectin." (PMID 36936928, 2023). "Leptin has many immunological effects relevant to infection risk, including immune senescence-inducing effects on B cells." (PMID 35455261, 2022). "Our present findings suggest that the low leptin levels observed in older women hospitalized in a rehabilitation ward contribute to increased susceptibility to infection." (PMID 35011102, 2022). "Our data shows that the function of leptin is very complex in that mutation of the lepb gene in an infection model leads to a very different signature set for inflammatory responses." (PMID 35933481, 2022). "Leptin-deficient (ob/ob) mice show increased susceptibility to infections, and resistance to induction of both active and passive EAE, associated in turn with progressive decline in autoreactive CD4+ T cell survival and reduced IFN-γ and IL-17 production." (PMID 36457996, 2022). "This “contributing” function of leptin is evident in malnourished or starving people, where low leptin (low reserves) is observed, which goes together with a high risk of infections." (PMID 35406000, 2022). "Earlier studies have shown that chronic leptin- and leptin-receptor deficiency are associated with enhanced infection susceptibility." (PMID 36479348, 2022). "In fact, leptin deficiency increases susceptibility to infections and infection-related mortality and is associated to cytokine dysregulation." (PMID 33804765, 2021). "While the mechanistic link between leptin resistance and infection susceptibility is complex and multifactorial, leptin’s actions through immune cells in the periphery and CNS, and dysregulation thereof, likely play a significant role." (PMID 34795562, 2021). "Intakes of dietary ω-3 fatty acids are associated with reduced lymphocyte proliferation and Th1 cell development, lower circulating levels of leptin, C-reactive protein and other pro-inflammatory cytokines, as well as a lower risk of infection." (PMID 32028957, 2020).